MMP2 (matrix metallopeptidase 2)
Diseases named in the same sentence as MMP2 in open-access papers (continued):
Sharing a sentence is not in itself a finding about the gene and the disease.
cancer (continued). "NF-κB, a transcription factor known for its role in promoting cancer cell survival and invasion, was found to be significantly activated upon S100A4 stimulation in this study, which demonstrated that NF-κB inhibition via Bay-11-7082 rescues hsa-miR-125b-5p expression, thereby reducing MMP-2 levels." (PMID 41155277, 2025). "This review provides a comprehensive overview of the anti-cancer potential of the most common single polyphenolic compounds, such as curcumin, resveratrol, epigallocatechin-3-gallate (EGCG), quercetin, and genistein, known to modulate the activity and expression of MMP-2 and MMP-9." (PMID 39335164, 2024). "Moreover, HMHA1 overexpression remarkably enhanced the total gelatinolytic activities by extracellular MMP-2 and MMP-9, suggesting that HMHA1 may promote ECM degradation and thereby facilitates hypoxic cancer cell invasion." (PMID 38740970, 2024). "However, eHsp90 is primarily known for enhancing the invasiveness of cancer cells by interacting with ECM proteins and ECM-modifying proteins present in the TME, such as Matrix Metalloproteinase (MMP)-2, MMP9, Plasminogen, Collagen-1, Fibronectin (FN), and LOX-like protein-2 (LOXL2)." (PMID 39594828, 2024). "The search included all studies published until May 2024 and used the following keywords, alone or in combination: cancer, cancer diseases, curcumin, EGCG, genistein, quercetin, resveratrol, polyphenols, polyphenolic compounds, chemoprevention, MMP-2, MMP-9, gelatinases, type IV collagenases." (PMID 39335164, 2024). "EA could inhibit the metastasis by downregulating MMP-2 and MMP-9 expression since matrix metalloproteinases (MMPs) are endopeptidases, capable of extracellular matrix (ECM) degradation, hence promoting migration, invasion, and metastasis of cancer cells." (PMID 37259418, 2023). "The regulatory role of RKIP in MMP1 and MMP2 expression appears to be through RKIP’s inhibitory regulation of the NF-kB pathway, as inhibition of this pathway nearly fully inhibits the increased invasive capabilities observed in cultured cancer cells when RKIP is lost." (PMID 36765912, 2023). "In addition, activated platelets secrete lysophosphatidic acid, which upregulates matrix metalloproteinase 2 (MMP2), MMP7, and MMP9 activities in cancer cells, then promote cancer progression by facilitating the detachment of cancer cells from their primary site and into the circulation." (PMID 37153586, 2023). "As matrix metalloproteinases (MMPs) mediate cancer cell invasion and metastasis in human malignancies, including OC38, in this study we aimed to explore whether irisin affects the mRNA expression level of MMP2 and MMP9 as two verified metastasis markers in OC." (PMID 36599894, 2023). "Moreover, the docking energy of BPU computationally scored − 9.0 kcal/mol with the human matrix metalloproteinase 2 (MMP-2) and − 7.8 kcal/mol with the human matrix metalloproteinase 9 (MMP-9), denoting promising binding results as compared to the existing drugs for cancer therapy." (PMID 38129413, 2023). "Upregulation of ErBb2 may either produce metastasis-related characteristics like angiogenesis or invasion, or it may promote curative resistance, ultimately deteriorating cancer cell metastasis and attempting distressing responses to cancer-curative MMP-9 and MMP-2 protein activities." (PMID 37845675, 2023). "Its major function in cancer progression is to directly degrade the extracellular matrix components, which are mainly type I–III collagen or indirectly type IV collagen through the activation of MMP-2 with a cooperative function of the tissue inhibitor of metalloproteinase-2 (TIMP-2)." (PMID 37681919, 2023).
cancer (continued). "MMP2/9 overexpression and enhanced fibronectin cleavage occurred during peritoneal colonisation, which could be inhibited by specific MMP inhibition, thereby reducing cancer cell attachment." (PMID 35954423, 2022). "Their differentiation is stimulated by chemotactic factors secreted by cancer cells to promote tumor progression such as proliferation induction, ECM remodeling, angiogenesis, and adaptive immune evasion, either by the release of EGF, or by the degradation of ECM proteins (MMP2 and MMP9)." (PMID 35205204, 2022). "Furthermore, miR-21 targets matrix metallopeptidase 2 (Mmp2) in cardiac fibroblasts of the infarcted heart via phosphatase and the tensin homolog (PTEN) pathway, suggesting the important signaling roles of miR-21 in both cancer and cardiovascular disease." (PMID 36428980, 2022). "And MMP-2 and S100A4 may be the key targets of STAT3 involved in cancer metastasis." (PMID 35513871, 2022). "Therefore, cellular function, migration, and invasion of cancer cells and EMT may be regulated by MMP9 and MMP2, and the expressions of upstream regulators such as AMPK, NF-κB, and TIMPs need to be further explored." (PMID 35770085, 2022). "Moreover, knockdown of WFDC2 decreased matrix metalloproteinase-2 (MMP-2) expression, both in vitro and in vivo, which indicated that WFDC2 may also contribute to cancer metastasis." (PMID 35924143, 2022). "Moreover, Stat3 can activate the transcription of MMP2, MMP9, and Snail in cancer cells." (PMID 35178453, 2022). "IL-17 has been found to promote migration, extracellular matrix degradation, and invasion of cancer cells, including GBM cells, through the activation of PI3K–AKT and STAT3 signaling, as well as through the elevation of expression of the matrix metalloproteinases MMP-2 and MMP-9." (PMID 35884700, 2022). "Additionally, there are mAbs designed for MMP-2 and MMP-9 that could prove efficacious for cancer treatment." (PMID 33810259, 2021). "MMP2 and MMP9 may play important roles in cancer cell migration and invasion." (PMID 34812264, 2021). "In addition, insulin mediates insulin receptors, up-regulates MMP-2 expression, stimulates insulin receptor substrate-1 (IRS-1), and then activates the PI3K/AKT and MAPK signaling pathways to promote cancer cell proliferation and enhance cancer cell migration ability." (PMID 34485124, 2021). "Moreover, the FAK-SRC complex might induce MMP2 and MMP9 and subsequently increase the invasiveness of cancer cells." (PMID 34589434, 2021). "Further, our co-expression analysis also showed that key EMT-related factors such as MMP2, MMP9, CDH2, TGFB1, and VIM were highly expressed when CHN1 was highly expressed, while CDH1 was expressed at lower levels, suggestive of a potential cancer-promoting function of CHN1." (PMID 34152250, 2021). "In an attempt to develop peptide-based gelatinase inhibitors to attenuate cancer progression, an in vitro phage display screen with purified MMP9 using a random peptide (CX5-8C) library was used to identify two cyclic decapeptides (CTTHWGFTLC (CTT) and CRRHWGFEFC) targeting MMP2 and MMP9." (PMID 33918106, 2021). "The results of meta-analyses suggest that polymorphisms in MMP-1, MMP-2, and MMP-7 may be associated with cancer risk in Asian or Latin-American populations, but not in European or Caucasian populations." (PMID 32765800, 2020). "Additionally, blocking MMP-2, cathepsin D, PAI-1, and Gal-1also reduced cancer cell invasion." (PMID 32984024, 2020). "Thus, our findings indicate that matrine may affect cancer invasion by down-regulation of MMP-9 and MMP-2 activities." (PMID 32630806, 2020). "Furthermore, sodium danshensu treatment decreased MMP-2 expression without altering MMP-9 expression in both these cancer cells." (PMID 33101201, 2020).
cancer (continued). "Within the heterogeneous microenvironment of tumors, the highly invasive cancer cells that over-express MMP-2, and stromal fibroblasts, are capable of pulling the less motile cancer cells that lack functional FAK thus promoting collective migration of the whole cancer cell cluster." (PMID 33321813, 2020). "Therefore, targeting MMP‐2 and/or MMP‐9 might provide a strategy for cancer treatment and prevention." (PMID 32180962, 2020). "The results indicate that HCT and PR extracts at non-toxic doses could inhibit cancer cell migration and invasion by decreasing the MMP-2 and -9 secretion." (PMID 32155880, 2020). "It was reported that SPP1 could regulate MMP-2 and MMP-9 expression and promote extracellular matrix degradation via activating αvβ-NF-κB pathway, and thus accelerate the growth, migration and invasion of cancer cells." (PMID 33240930, 2020). "Intriguingly, the matrix metalloproteinases (e.g. MMP2, 9, and 14) capable of degrading collagens and proteoglycans were also found to be upregulated in omental metastases, consistent with the idea that ECM degradation and remodeling are essential steps for cancer cell invasion." (PMID 33026975, 2020). "Nevertheless, there is no data on whether GPCs could influence MMP2 expression nor a more thorough description of how these expressions would be altered in different kinds of cancer, such as GBM." (PMID 32180897, 2020). "Thus, suppressing MMP‐2 and MMP‐9 can be a critical step to inhibit metastasis in cancer." (PMID 33133558, 2020). "Hence, it is quite probable that Aloe species might inhibit enzymatic activity of MMP-2 (72 kDa) and MMP-9 (92 kDa) in cancer-related situations." (PMID 33308217, 2020). "The inhibition of MMP2 and MMP9 could suppress the metastasis of cancer cells." (PMID 33228670, 2020). "Moreover, upregulation of the Fn1, Mmp2, and Snai1 mRNAs, which are hallmarks of tube-forming growth in PDAC, was demonstrated in a mouse model of carcinogenesis showing rapid progression because of the aggressive invasion of tube-forming cancer." (PMID 31375695, 2019). "Besides, the mRNA expression of matrix metalloproteinase-2 (MMP-2) and the vascular endothelial growth factor (VEGF) underwent down-regulation after STAT3 knockdown, demonstrating the pivotal role of STAT proteins in progression of cancer cells." (PMID 31569687, 2019). "In our experiments, we confirmed that the protein expression of VEGF, MMP-2, MMP-7 and MMP-9 in mouse GC tissue was significantly increased after activation of ADRB signalling under the condition of chronic stress; thus, these proteins play a role in promoting cancer and metastasis." (PMID 31624248, 2019). "Moreover, an earlier study showed that Sp1 upregulates MMP2 and MMP9 in cancer cells." (PMID 30845713, 2019). "Therefore, LOX, MMP-2, and MMP-9 are highly expressed in many malignant tumors." (PMID 31777578, 2019). "Since invasion of trophoblasts, like cancer cells, is closely dependent on the expression of matrix metalloproteinases (MMPs), which can degrade the extracellular matrix (ECM), we assumed an alteration in the mRNA level of MMP2 in cells treated with siRNA against RITA (siRITA)." (PMID 31766533, 2019). "In these spatial domains, we represent the MMP-2 concentration and the ECM density at position (x, y) at time t by the continuous functions m(t, x, y) and w(t, x, y), respectively, while capturing the spatiotemporal evolution of epithelial-like and mesenchymal-like cancer cells individually." (PMID 30903592, 2019). "Interestingly, Sp1 is also known to upregulate MMP2 and MMP9 in cancer cells." (PMID 30845713, 2019). "Inhibition of MMP-2 and MMP-9 may be a suitable therapeutic option for cancer." (PMID 31783821, 2019). "Moreover, Tan IIA inhibited NF-κB signalling and expression of MMP-2 and MMP-9, and increased levels of tissue inhibitor of matrix metalloproteinases type 1 and 2 (TIMP-1 and TIMP-2), therefore suppressed invasion and metastasis of cancer cells." (PMID 30373594, 2018).
cancer (continued). "Matrix metalloproteinases (MMPs), such as MMP-2 and MMP-9, modulate cell–cell and cell–extracellular matrix interactions via degrading various cell adhesion molecules, thereby playing vital roles in cancer cell migration, invasion, metastasis, and angiogenesis." (PMID 29867200, 2018). "In our study, we confirmed that Zey treatment markedly reduced MMP-2/9 expression in SGC7901 and MGC803 cells, which implied that Zey, as an inhibitor of MMP expression, may be developed into an early treatment to prevent cancer metastasis." (PMID 30150551, 2018). "In addition, the cancer cell-derived osteoclast-activating factors MCSF, IL-6, IL-8, RANKL, MMP2, MMP13, RUNX2 and PTHrP are significantly down-regulated in MDA-MB-231 cells transfected with miR-124 mimic and up-regulated in MCF7 cells transfected with miR-124 inhibitor." (PMID 29343249, 2018). "GBM cells, and cancer cells originating from other organs (e.g. prostate, cervix), having high expression of MMP2, were subjected to a 4-day culture with and without ZR30, and the proteins precipitated from 2-day conditioned medium were examined by gelatin zymography." (PMID 29290950, 2017). "Besides, only MMP2 and MMP9 were found to involve into cancer." (PMID 28427222, 2017). "Herein we demonstrated that ginsenoside Ro inhibited migration and invasion ability of cancer cells and their adhesion to human endothelial cells via its specific inhibition of expression of integrin αvβ6, MMP-2 and MMP-9 without producing any significant cytotoxicity to the tested cells." (PMID 28634392, 2017). "Thus, MMP-2 and MMP-9 have potential use for the detection of cervical lesions and cancer." (PMID 29267213, 2017). "However, how Rab40b regulates targeted MMP2 and MMP9 secretion and localized ECM remodeling remains to be understood, and the machinery that regulates levels of Rab40b in cancer cells is also unknown." (PMID 27789576, 2016). "In addition, data mining results from The Comparative Toxicogenomics Database indicates that bisphosphonate down-regulates expression of LOX, MMP2, COL1A1 and SPARC, which means bisphosphonate may suppress cancer metastasis by targeting these four genes." (PMID 27147578, 2016). "Moreover, we also determined that BX357664 could suppress the expression of MMP2 and MMP9 in RCC cells (p < 0.05), providing more evidence for the inhibitory role of BX357664 in cancer metastasis in RCC." (PMID 27806310, 2016). "Moreover, our analysis indicates that LOX is likely co-expressed with MMP2, COL1A1 and SPARC, all of which contribute to initiating cancer metastasis and EMT, and that bisphosphonates inhibit MMP2 activity, COL1A1-driven osteoporotic fracture and SPARC-stimulated EMT." (PMID 27147578, 2016). "To check whether PARP-1 has any role in the regulation of metastatic nature of cancer cells after treatment with carbon ion exposure, we looked into the activities and expression of two major matrix metalloproteinases, MMP-2 and MMP-9, which are highly activated during cancer metastasis." (PMID 27659937, 2016). "Among MMPs, MMP-2 (gelatinase A) and MMP-9 (gelatinase B) are vital enzymes involved in the degradation of gelatin, collagen and laminin, main components of ECM and high expressions of them are indicators of high invasive potential of cancer cells and are related to poor prognosis of patients." (PMID 27144433, 2016). "Our results with the XTEN-fused Killin fragment presented in this study, which bears a cell-penetrating peptide and enzyme-specific cleavage site, is able to arrest cancer cell growth and induce apoptosis in vitro, while normal liver cells and cells without MMP-2 expression are almost unaffected." (PMID 27295081, 2016). "Besides HT-1080 cells, another cancer cell line with high basal expression of MMP-2, HeLa and, noncancerous BRL-3A cells, which are derived from normal rat liver, were chosen for broader examination." (PMID 27295081, 2016).
cancer (continued). "Given that ubiquitin-dependent protein degradation has emerged as an important modulator of invadopodia and cancer metastasis, the identification of Rab40b-SOCS-interacting proteins might shed more light on the mechanisms that regulate MMP2 and MMP9 targeting during cancer cell invasion." (PMID 27789576, 2016). "We examined the levels of MMP-2 and MMP-9, our data demonstrated that knockdown of HCRP-1 may promote cancer cell migration and invasion through increased expression of MMP-2 but not the MMP-9." (PMID 26304749, 2015). "Therefore, inhibiting the migration or invasion mediated by MMP-2, MMP-9, or u-PA could putatively provide a preventive measure against cancer metastasis." (PMID 25605016, 2015). "Therefore, the expressional suppression of MMP-2 and MMP-9 may result in the inhibition of migration in cancer cells." (PMID 25634589, 2015). "We found that MMP-2 decreased by inhibiting CD44 via blocking mTOR signaling, whereas MMP-9 was not, demonstrating that the MMPs may have diverse roles in the signaling pathways of various cancers." (PMID 26202311, 2015). "Endothelin-1 (ET-1) has been involved in many cancer-related processes, such as proliferation, angiogenesis, EMT and metastasis, many of these exerted through activation of multiple signaling cascades, including the Wnt/β-catenin pathway and its known targets such as cyclin D1, MMP2 and survivin." (PMID 26543229, 2015). "Moreover, expression of the matrix metalloproteinases coded by the MMP2, MMP9, and MMP14 genes confers these cells the ability to degrade extracellular matrix proteins, an important step in various stages of cancer progression, including angiogenesis, invasiveness, and metastasis." (PMID 26110651, 2015). "Real-time PCR revealed significantly higher expression of the three most prominent cancer related MMPs—MMP1, MMP2 and MT1-MMP—in WM266-4 cells compared to 501mel cells, suggesting that during cooperative invasion, WM266-4 cells could adopt a role similar to fibroblasts." (PMID 25066122, 2014). "Our results suggested that the protein level and activity of MMP-2, a Type IV collagenase which was critical in cancer cell invasion and metastasis, was attenuated in the ATF3-expressing cells, suggesting that MMP-2 might be a downstream molecule of ATF3 function." (PMID 25149542, 2014). "Several well-differentiated HCC cells express MT1-MMP and gradually small amounts of MMP-2 and MMP-9, probably stimulated by inflammatory cytokines or TGF-β, which may participate in the stromal invasion or the formation of the thick capsule of cancer nodules." (PMID 24978432, 2014). "MMP-2 localizes at the migrating edge of TLX-expressing TIC clusters in the xenograft sections of human NB-TICs, suggesting its importance for migratory activities of cancer cells, which may result in invasiveness leading to metastasis." (PMID 25356871, 2014). "Therefore, MMP2 gene expression was significantly different between mucinous and nonmucinous carcinomas (P = 0.001) and in patients aged over 60 years (P < 0.0001)." (PMID 24737953, 2014). "Therefore, MMP-2 may be the CCL3-responsive mediator, and may degrade the ECM leading to subsequent cancer migration and metastasis." (PMID 24047437, 2013). "Therefore, MMP-2 may be the HGF-responsive mediator, and its degradation of ECM may lead to subsequent cancer migration and metastasis." (PMID 23320110, 2013). "In addition, MMP-2 and MMP-9 expression levels were found to be significantly lower in the cells treated with combination therapy, indicating that the treatment was controlling cancer cell invasion and metastasis." (PMID 23536878, 2013). "The implications of MMP-2 activation by MMP-14 and the tissue inhibitor of metalloproteinases-2 are considered alongside the effect the architecture of the matrix may have when applied to a model of cancer invasion." (PMID 23565505, 2013).